CCL25 (C-C motif chemokine ligand 25)
Description:
Potentially involved in T-cell development. Recombinant protein shows chemotactic activity on thymocytes, macrophages, THP-1 cells, and dendritics cells but is inactive on peripheral blood lymphocytes and neutrophils. Binds to CCR9. Isoform 2 is an antagonist of isoform 1. Binds to atypical chemokine receptor ACKR4 and mediates the recruitment of beta-arrestin (ARRB1/2) to ACKR4.
Synonyms: SCYA25; TECK; Ckb15; Ck beta-15; TECKvar
Tractability: Antibody: its Gene Ontology location is reachable by antibodies, with high confidence; UniProt places it where antibodies can reach, with medium confidence; UniProt predicts a signal peptide or a membrane-spanning region.
Gene: Protein-coding gene on chromosome 19 (8,052,293 to 8,062,665, forward strand). Ensembl gene ENSG00000131142.
Subcellular location: Secreted
Pathways (Reactome):
Signal Transduction: Chemokine receptors bind chemokines; G alpha (i) signalling events
Gene Ontology:
Molecular function: CCR10 chemokine receptor binding; chemokine activity; chemokine receptor binding; protein binding; CCR chemokine receptor binding; hormone activity
Biological process: cell chemotaxis; G protein-coupled receptor signaling pathway; negative regulation of leukocyte tethering or rolling; positive regulation of cell-matrix adhesion; antimicrobial humoral immune response mediated by antimicrobial peptide; cell surface receptor signaling pathway; chemokine-mediated signaling pathway; chemotaxis; eosinophil chemotaxis; immune response; inflammatory response; positive regulation of cell migration; immune system process
Cellular component: extracellular region
Genetic constraint (gnomAD): Loss-of-function variants: 16 observed, 15.5 expected, observed/expected ratio (o/e) 1.03, 90% interval 0.7 to 1.56. The upper end of that interval is the gene's LOEUF score, 1.56, which puts it in group 6 of 6, group 1 being the genes least tolerant of losing a copy. Missense variants: 137 observed, 146.62 expected, observed/expected ratio (o/e) 0.93, 90% interval 0.81 to 1.08. Synonymous variants: 61 observed, 58.6 expected, observed/expected ratio (o/e) 1.04, 90% interval 0.85 to 1.29.
Homologues: Orthologues: chimpanzee CCL25 (98% identical), pig CCL25 (59% identical), dog CCL25 (47% identical), zebrafish cxcl32b.1 (16% identical). Paralogues in human: CCL21 (23% identical), CCL11 (21% identical), CX3CL1 (19% identical), CCL16 (18% identical), CCL26 (18% identical), CCL7 (18% identical), CCL8 (17% identical), CCL1 (17% identical), CCL13 (17% identical), CCL2 (17% identical), CCL24 (17% identical), CCL20 (16% identical), and 14 more.
Diseases named in the same sentence as CCL25 in open-access papers:
CCL25 is named in the same sentence as 121 diseases in open-access papers, as found by Europe PMC text mining. Sharing a sentence is not in itself a finding about the gene and the disease. The quoted sentences say what the papers report.
breast carcinoma (22 papers, 2011 to 2024). "CCL25 is produced by tumor-associated cells or cancer cells, such as breast cancer cells and pancreatic cancer cells." (PMID 34771505, 2021). "CCL7, CCL17, CCL20 and CCL25 are significantly more elevated in AA breast cancer patients compared to CA patients." (PMID 32824813, 2020). "The expression of CCR9 and CCL25 have been identified in some solid tumors, including ovarian cancer 9, breast cancer 10, prostate cancer 11, pancreatic cancer 12 and esophageal cancer." (PMID 32308544, 2020). "Higher expression levels of CCL17 and CCL25 in breast cancer patients have been attributed to poor overall survival in the AA population, but no such correlation has been observed in the CA population." (PMID 32824813, 2020). "Together, CCL17 and CCL25 in AA breast cancer patients decrease overall survival, while high CCL8 decreases overall survival in CA patients." (PMID 32824813, 2020). "The CXCL12/CXCR4 axis is strongly correlated with breast cancer aggressiveness and metastasis, whereas the CCL25/CCR9 axis provides chemotherapy resistance to breast cancer cells." (PMID 31616626, 2019). "Moreover, it was first published in 2022 that the level of CCL25 is increased in the cerebrospinal fluid of patients who developed neuropathic pain after breast cancer surgery, which suggests that CCL25 has pronociceptive effects." (PMID 38612597, 2024). "On the other hand, studies have shown that in breast cancer, CCL25 increases the expression of matrix metalloproteinases (MMPs), including MMP-2, MMP-3, MMP-9 and MMP-10, which effectively degrade the extracellular matrix (ECM) and promote the invasion of cancer cells." (PMID 36003306, 2022). "However, CCL25 has served as an indicator of poor prognosis in AA breast cancer patients; its expression was correlated with improved overall survival in CA breast cancer patients." (PMID 32824813, 2020). "Furthermore, CCL25 can mediate migration, invasion and matrix metalloproteinase expression in breast cancer cell lines." (PMID 28987144, 2017). "CCL25 and its receptor C-C motif chemokine receptor 9 (CCR9) are overexpressed in cancers such as leukemia, ovarian cancer, breast cancer, prostate cancer, liver cancer, lung cancer, and melanoma." (PMID 35240026, 2022). "CCL25/CCR9 signaling can promote the migration and invasion of breast cancer cells to the bone by regulating numerous markers of epithelial–mesenchymal transition (EMT)." (PMID 33435254, 2021). "CCR9/CCL25 also has an important role in tumor invasion and metastasis by promoting EMT in liver, non-small cell lung cancer, and breast cancer cell lines." (PMID 33034614, 2020). "CCL25/CCR9 signaling enhanced invasion and metastasis in breast cancer, melanoma, and ovarian cancer." (PMID 30723697, 2018). "CCR9 overexpression is also possibly correlated with invasiveness in response to CCL25 in T-ALL, prostate cancer, breast cancer, and melanomas." (PMID 28380463, 2017). "The role of the CCL25/CCR9 axis in the development of neuropathy requires research; however, in 2022, it was shown that in the CSF of patients who developed postoperative neuropathic pain after breast cancer surgery, an enhanced level of CCL25 was observed." (PMID 37570736, 2023). "Fast Activated Cell-based ELISA (FACE) assay was used to quantify In situ activation of PI3Kp85, AktSer473, GSK-3βSer9 and FKHRThr24 in breast cancer cells with or without cisplatin treatment in presence or absence of CCL25." (PMID 21539750, 2011). "Interestingly, shRNA-mediated stable knockdown of CCR9 did not affect CCL25 production by MCF7 breast cancer cells (Fig6A)." (PMID 25691366, 2015).
colitis (20 papers, 2011 to 2025). Inflammation of the colon. "CCL25 expression in the colon is associated with high frequencies of CCR9+ tissue-infiltrating effector T-cells in patients with colitis." (PMID 34512631, 2021). "We used a murine model of oxazolone-induced colitis to investigate the potential regulatory roles of CCL25/CCR9 interactions in NKT cells and the underlying mechanisms involved." (PMID 24936795, 2014). "The most compelling argument for a physiologic role of CCL25/CCR9 interactions during an inflammatory response in the colon is derived from the increased susceptibility to colitis and the high mortality rate observed in CCR9−/− animals." (PMID 21283540, 2011). "CCR9–/– and CCL25–/– mice are more susceptible to acute DSS colitis than WT controls." (PMID 34490243, 2021). "Moreover, CCL25 expression in the colon is associated with high frequencies of CCR9+ tissue-infiltrating effector T-cells in patients with colitis, which exhibit increased potential toward adhesion to liver endothelium." (PMID 26873648, 2016). "Like CCR9−/− animals, CCL25−/− mice were more susceptible to DSS colitis." (PMID 21283540, 2011). "In dextran sulphate sodium-induced colitis models in Kunming male mice, G. lemaneiformis inhibited CCL-25 and CCR-9 levels, increased CD40 and TGF-β1 and modulated the gut microbiota, suggesting its use as a functional food for ulcerative colitis patients." (PMID 40077614, 2025). "Although CCR9–/– T cells traffic to the colon and induce severe colitis similar to WT T cells, naive WT T cells induce more severe disease in recipient animals devoid of CCL25 expression." (PMID 34490243, 2021). "Nevertheless, certain studies do report colonic Ccl25 transcripts in spontaneous murine models of colitis, as well as colonic inflammation induced by dextran sulphate sodium and oxazolone." (PMID 26873648, 2016). "Colonic CCL25 levels in mice with severe colitis, defined by persistent, severe diarrhea and wasting, increased more than 60-fold (P < 0.01), compared to presymptomatic mdr1a−/− mice, and were more than 350-fold higher than in wild-type mice (P < 0.05)." (PMID 26457007, 2015). "Colonic CCL25 protein levels continued to increase dramatically as mice developed severe colitis, and the highest levels of colonic CCL25 protein were found in those mice with the most severe disease." (PMID 26457007, 2015). "In the present study, we evaluated the role of CCL25/CCR9 interactions in the regulation of NKT cells in a model of oxazolone-induced colitis." (PMID 24936795, 2014). "CCR9- or CCL25-deficient animals or antibody-mediated neutralization of these factors are needed in future studies to definitively define the function and mechanism of CCL25/CCR9 interactions in the regulation of iNKT cells during oxazolone-induced colitis." (PMID 24936795, 2014). "Our data show that CCL25 expression increases during DSS colitis, suggesting a regulatory role of CCL25/CCR9 interactions during large intestinal inflammation." (PMID 21283540, 2011). "Since similar results were obtained with the CCL25−/− strain, these data show that the exacerbated colitis is a consequence of impaired CCL25/CCR9 interaction." (PMID 21283540, 2011). "The results presented in this study identify a novel role of CCL25/CCR9 interactions in the pathogenesis of a well-established acute colitis model mediated by oral administration of DSS." (PMID 21283540, 2011). "CCL25 expression has been shown to correlate with the presence and severity of colitis." (PMID 38505585, 2024). "CCL25-dependent migration into the small intestine of Siglec-H ko pDCs may be affected in inflammatory conditions such as colitis." (PMID 34497606, 2021). "Yet, another study by Trivedi and colleagues has shown that the colonic expression of the CCR9 ligand CCL25 is upregulated in patients with active colitis and also correlates with the endoscopic Mayo score." (PMID 31356607, 2019).
colitis (continued). "Similarly, inflammation can increase the expression of CCL25 in colitis where CCL25 expression correlates with inflammation in the GIT." (PMID 30662436, 2018). "Indeed, CCL25 mRNA expression was detected in resected colonic tissue from patients with refractory colitis (n = 10; median expression relative to GUS-β: 9.6ε−4; IQR 2.0ε−4 – 3.2ε−3) but not in normal colonic tissue (n = 10)." (PMID 26873648, 2016). "On achieving remission from a colitis flare, the colonic CCL25 gradient is attenuated, and primed mucosal CCR9+ lymphocytes now become permissive to recruitment to the liver sinusoids in response to aberrant hepatic endothelial CCL25 expression – as observed in the PSC liver." (PMID 26873648, 2016). "Collectively, these results suggest that CCR9/CCL25 interactions are not only involved in colitis pathogenesis but also correlate with colonic inflammatory burden; further supporting the existence of overlapping mucosal lymphocyte recruitment pathways between the inflamed colon and liver." (PMID 26873648, 2016). "If CCL25 expression is driven by colitis activity, and colonic CCR9+ T-cells are responsible for driving hepatobiliary inflammation in PSC, then it should follow that the risk of PSC increases with intestinal activity; an observation which does not hold true clinically." (PMID 26873648, 2016). "Herein, we show that colonic CCL25 expression is not only upregulated in patients with active colitis, but strongly correlates with endoscopic Mayo score and mucosal TNFα expression." (PMID 26873648, 2016). "In 16-week-old mdr1a−/− mice, which exhibited no overt symptoms (diarrhea, weight loss) of colitis, colonic CCL25 levels were significantly higher than in age-matched wild-type mice." (PMID 26457007, 2015). "In this study, we investigated the role of CCR9 and CCL25 in colonic inflammation." (PMID 26457007, 2015). "The results show that CCL25 and CCR9 are both expressed in the large intestine and are upregulated during DSS colitis." (PMID 34490243, 2021). "This is important as the CCR9/CCL25 pathway is being targeted to treat inflammatory bowel disease (IBD) and evidence of upregulation in active colitis would support clinical studies of anti-CCR9 therapy." (PMID 26873648, 2016). "CCL25 mRNA was recently detected in mouse colon and was found to be upregulated in the DSS model of acute colitis." (PMID 26457007, 2015). "We found that the expressions of NK1.1, CCL25 and CCR9 were significantly increased during oxazolone-induced colitis." (PMID 24936795, 2014). "To examine the correlation between CCL25/CCR9 interactions and NKT cells, we used oxazolone-induced colitis in mice." (PMID 24936795, 2014). "And, the mRNA expression levels of NK1.1, CCL25 and CCR9 were increased in oxazolone-induced colitis in mice." (PMID 24936795, 2014). "Upregulated mucosal expression of numerous chemokines and their counter receptors including CXCL8 (IL-8)/CXCR2, CXCL9,10,11/CXCR3, CCL25/CCR9, CCL19,21/CCR7, and CCL20/CCR6 is evident in active IBD and in models of colitis." (PMID 22162719, 2012). "Although CCL25 is largely absent from the non-inflamed human colon, expression is markedly upregulated in colitis and correlates with inflammatory activity." (PMID 34512631, 2021). "We now show that although CCL25 is largely absent from non-inflamed human colon, expression is markedly upregulated in colitis and correlates with inflammatory activity." (PMID 26873648, 2016). "CCL25-/- Rag-/- mice developed more severe disease compared to that in WT Rag-/- mice on transfer of CD45RBhi T cells, possibly meaning that innate CCR9 expression also regulates colitis development." (PMID 26230654, 2015). "To determine whether colitis affects the expression levels of NK1.1, CCL25 and CCR9, we analyzed the mRNA expression levels using qPCR." (PMID 24936795, 2014). "Our study suggests that CCL25/CCR9 interactions may promote the induction and function of iNKT cells during oxazolone-induced colitis." (PMID 24936795, 2014).
colitis (continued). "Importantly, we demonstrated that human UC and UC-like colitis upregulated the expression of NKT, CCL25 and CCR9 in both humans and mice." (PMID 24936795, 2014). "In conclusion, this study has shown that CCL25/CCR9 interactions may promote the induction and function of iNKT cells during oxazolone-induced colitis." (PMID 24936795, 2014). "It is reasonable to speculate that CCL25 signaling through CCR9 might induce iNKT cells to migrate into the colon during human UC and UC-like colitis." (PMID 24936795, 2014). "It is our hypothesis that CCL25/CCR9 interactions promote the induction and function of iNKT cells during oxazolone-induced colitis." (PMID 24936795, 2014). "However, recent data showed that, although colonic levels of CCL25 are low in healthy mice, they are significantly upregulated upon DSS-induced colitis." (PMID 22162719, 2012). "Interestingly, the expression of a set of genes encoding chemokines involved in homeostatic processes, including CCL21, CCL25, CCL27 and CCL28, was gradually down-regulated in our TNBS colitis model." (PMID 23226271, 2012). "CCL25 and CCR9 are both expressed in the large intestine and are upregulated during DSS colitis." (PMID 21283540, 2011). "Increased IBD scores, more pronounced weight loss, a delay in recovery from acute inflammation and the inability to regain initial body weight during the experimental time period support the critical role for CCL25/CCR9 dependent trafficking events during the acute and recovery phase of DSS colitis." (PMID 21283540, 2011). "However, the role of CCL25/CCR9 interactions in the regulation of NKT cells during colitis has not been studied." (PMID 24936795, 2014). "However, prior to this study, no work has been presented on CCL25/CCR9 interactions in an experimental acute colitis mouse model mediated by DSS exposure." (PMID 21283540, 2011). "Given the fact that CCR9-expressing pDCs are inducers of T regulatory cell functions, further examination of Tregs distribution and function would determine whether Tregs play a role in DSS colitis recovery and whether or not it is CCL25/CCR9 dependent." (PMID 21283540, 2011). "Alternately, interactions between CCL25 and CCR9, known to specifically target lymphocytes to the small intestine compartment, have recently been found to regulate large intestinal immunity in a chemically-induced model of colitis, and may play a role in in vivo immunity to Trichuris." (PMID 21573179, 2011).